MTOR (mechanistic target of rapamycin kinase)
Diseases named in the same sentence as MTOR in open-access papers (continued):
Sharing a sentence is not in itself a finding about the gene and the disease.
cancer (continued). "The results overall suggest that the AMPK pathway could act synergistically with PPAR and mTOR signaling to influence cancer progression significantly." (PMID 32807122, 2020). "Because clonogenicity is a sensitive indicator of undifferentiated cancer stem cells (CSCs), this result implies that mTOR signaling may be required for CSC self-renewal and anchorage-independent growth in order to maintain CSC populations in tumor tissues." (PMID 32676162, 2020). "The interest in mTOR targeting may improve immune response against cancer and develop new therapeutic strategy." (PMID 33014055, 2020). "Recent findings suggest that dual targeting of mTOR has the ability to overcome resistance to ionizing radiation and improve the anticancer efficacy of treatment in various cancer cell types in in vitro and in vivo models of cancer." (PMID 32239160, 2020). "However, several reports suggest that apoptosis has a controversial role in the anti-cancer effect of dual AKT/mTOR inhibitors." (PMID 33659215, 2020). "Given the critical involvement of mTOR in EGFR-mut cancers, it is possible that TF might be a molecular and functional target of mTOR complexes in these tumors." (PMID 32923403, 2020). "An interesting finding is MMP9, MYC, MAPK1, MTOR are all in Proteoglycans in cancer." (PMID 32958005, 2020). "Finally, we discuss combination targeting of MAPK/ERK-Hippo/MST-PI3K/AKT/MTOR signaling pathways for improve outcomes of current cancer therapies." (PMID 32375238, 2020). "Combination therapy with PI3K/AKT/mTOR pathway and autophagy inhibitors for cancer treatment." (PMID 33123479, 2020). "Interestingly, QGP-1 spheroid cells, which exhibited cancer stem cell-like features, exhibited lower expression of Prdx2 and mTOR." (PMID 33182509, 2020). "In addition, the correlation between these PI3K/AKT/mTOR signaling pathway members and specific clinicopathological parameters of cancer, such as cancer stage, was also explored." (PMID 32547875, 2020). "Additionally, glucose regulated protein 78 (GRP78) interacts with α2-macroglobulin to activate AKT1 via PDK1, as well as mTOR to enhance cancer cell proliferation and radiotherapy resistance in GBM." (PMID 32333246, 2020). "The Akt/mTOR pathway is a common oncogenic pathway in various cancers, BC included." (PMID 32908134, 2020). "The first line of RCC treatment was selected by targeting universal cancer characteristics, such as the fast growth of cancer, based on growth signaling including mTOR, vascular endothelial growth factor (VEGF), and platelet-derived growth factor (PDGF) pathways." (PMID 32260198, 2020). "mTor signaling is involved in the regulation of numerous basic physiological processes such as metabolism, cell survival, and autophagy and is aberrantly overactivated in many cancers." (PMID 32883016, 2020). "In addition to this, cancer cells can evade controls within the cell by mTOR and AMPK complexes, in which complexes regulate stress due to oxygen depletion and periods of intense metabolism." (PMID 33149807, 2020). "Likewise, we detected a reduction in the expression of proteins related to PI3K/AKT/mTOR pathway in the cancer cells treated with 0.5 μM GA for 24 hours or 48 hours." (PMID 32913452, 2020). "Hence, targeting the PI3K/Akt/mTOR pathway in cancer cells would directly influence the mitochondrial function and trigger cell death." (PMID 33028364, 2020). "Although for various cancers, overexpression of efflux pumps is often associated with chemoresistance, deregulation of the PI3K/Akt/mTOR pathway contributes to the resistance of HCCs to drugs acting on microtubules, including vincristine, colchicine, and paclitaxel." (PMID 32260550, 2020). "In addition to providing carbon and nitrogen for macromolecular synthesis in cancer cells, glutamine also drives the uptake of EAAs and activates the mammalian target of rapamycin (mTOR) to promote tumor growth." (PMID 33117704, 2020).
cancer (continued). "The phosphatidylinositol-3-kinase (PI3K)/Akt and mammalian target of rapamycin (mTOR) signaling pathways were found to be potentially affected by m6A modification in most human cancers, including GI cancer, which was further verified by m6A-Seq and phospho-MAPK array." (PMID 32863943, 2020). "The PI3K/AKT/mTOR pathway is an intracellular signaling pathway mediating cell growth, proliferation, quiescence metabolism, survival, autophagy, and angiogenesis, and it has been reported to be involved in human cancer initiation." (PMID 32102330, 2020). "Interestingly, in response to low-nutrient status of cancer cells, the recruitment of mTOR to late endosomes/lysosomes is inhibited, further promoting ligand-bound α5β1 internalization and trafficking to lysosomes." (PMID 33195279, 2020). "Recently, mTOR has become a new target for cancer treatment." (PMID 32092870, 2020). "mTOR is a good example of a target which has experienced “indication-hopping,” having been developed for immunosuppression and immunomodulation and then as an anti-cancer and inhibitor of cellular senescence." (PMID 32733473, 2020). "Aberrant mTOR signaling provides the cancer cells with abundant amount of energy." (PMID 33292283, 2020). "mTOR is a key molecule that mediates rapid protein synthesis during cancer progression." (PMID 32782783, 2020). "PI3K/AKT/mTOR signaling pathway could regulate apoptosis and autophagy in cancer cells and is molecular targets for cancer therapy." (PMID 33123313, 2020). "Therefore, combined therapies with mTOR inhibitors and other target inhibitors are under investigation in preclinical and clinical trials in various cancers." (PMID 32517736, 2020). "AKT, a Serine/Threonine kinase, is a key component in numerous processes, can phosphorylate and then regulate vital downstream effector molecules, including FOXO, mTOR, GSK3b, and promote cancer cell growth, metabolism and survival and induce EMT and metastasis." (PMID 33088219, 2020). "Moreover, the inhibition of HIF-1α and VEGF expression both at mRNA and protein levels has been reported to suppress tumor growth, whereas targeting mTOR/HIF-1α/VEGF can be considered as a promising strategy in anti-cancer therapy." (PMID 32252351, 2020). "The PI3K/AKT/mTOR signaling pathway plays a key role in cancer metastasis." (PMID 32070055, 2020). "Of note, the PI3K/Akt and mTOR pathways were found universally altered in different cancers." (PMID 32863943, 2020). "•The mechanistic target of rapamycin (mTOR) is an attractive drug target for cancer therapy." (PMID 33142217, 2020). "The mTOR inhibitor temsirolimus can down-regulate the expression of tumor hypoxia-inducing factor and block the cell cycle in G1 phase to inhibit the growth of cancer cells and tumor angiogenesis." (PMID 32175074, 2020). "Moreover, these Akt/mTOR inhibitors enhanced cancer cell sensitivity to adriamycin, thereby leading to a significantly increased ratio of apoptotic cells expressing microRNA‐221 (P < .05)." (PMID 31899608, 2020). "LncRNA could act as specific miRNA sponge and induce activation of miRNA-mediated cancer-associated signaling pathways, such as Wnt/β-catenin and PI3K/AKT/mTOR." (PMID 32905397, 2020). "NF-κB and mTOR are well-known promising therapeutic targets for cancer." (PMID 33234722, 2020). "Preclinical studies have suggested that targeting mTOR could improve the efficacy of EGFR inhibitors in various human cancers, including TNBC." (PMID 32286420, 2020). "Moreover, fasting, calorie restriction and ketogenic diet affect the response to anti-cancer therapy, especially leading to reduced Akt/mTOR and Ras signaling in normal cells." (PMID 33027921, 2020).
cancer (continued). "Notably, previous studies demonstrated that HMGA1 knockdown increased autophagosome formation by constraining the activity of the mTOR pathway in cancer cells." (PMID 33536877, 2020). "It was found that increased mTOR nuclear localization might be related to poor prognosis of different types of cancer." (PMID 33260691, 2020). "Hence, inhibition of mTOR is one of the crucial therapeutic steps in the course of cancer treatment." (PMID 33067464, 2020). "In addition to having activity against many cancer cell lines, RapaLinks are effective against cancerous cells that are resistant to first or second generation mTOR inhibitors." (PMID 32373584, 2020). "This gene is involved in PI3K/AKT/mTOR pathway by mediation of glucose intake in cancer cells." (PMID 32013265, 2020). "Currently, mTOR inhibitors are in clinical use as immunosuppressants and anti-cancer drugs, and due to crucial role of the kinase in many illnesses, it is expected that mTOR inhibitors may have a broader application for other diseases." (PMID 32679743, 2020). "The mTOR signaling pathway is frequently deregulated in cancer and metabolic diseases." (PMID 32070029, 2020). "In addition to its link to cancer, the mTOR pathway regulates major cellular processes and is implicated in several other pathological conditions such as obesity, type 2 diabetes, and neurodegeneration." (PMID 31586300, 2020). "The most effective combinations of therapy for glycolysis cancer type are +mTOR and +NOX." (PMID 32276228, 2020). "Considering the significant role of the mTOR signaling pathway in many types of cancer 38-40, mTOR inhibitors may be effective in HCC patients with low SLFN11 expression." (PMID 32292519, 2020). "mTOR/AKT/PI3K is one of the most important signal transduction pathway in human cancer cells." (PMID 33173419, 2020). "MTOR is a serine/threonine protein kinase that participates in physiological processes and pathological reactions by regulating protein synthesis and is related to the pathogenesis of cancer." (PMID 33335853, 2020). "Interestingly, reactivation of AKT/mTOR signaling by using small molecule PI3K antagonists activates the transport of energy-active mitochondria to the cortical cytoskeleton of cancer cells, therefore heightening tumor cell invasion." (PMID 33489906, 2020). "Through both the post-translational regulation and induction of transcriptional programs, the dysregulated PI3K-Akt-mTOR pathway coordinates the uptake and utilization of multiple nutrient lipids supporting the enhanced growth and proliferation of cancer cells." (PMID 32180008, 2020). "GSEA indicated that multiple cancer signaling pathways (mTOR pathway, GSK3 pathway, EIF4 pathway, CHREBP2 pathway, MET pathway, NFAT pathway, FAS pathway, EDG1 pathway, AKT pathway, and CTCF pathway) were differentially enriched in YTHDF2 increased expression phenotype." (PMID 33102202, 2020). "Thus, the PI3K and mTOR pathways are recognized as promising targets for small-molecule inhibitors that improve treatment outcomes for various cancers, including GBM." (PMID 33013390, 2020). "However, clinical trials are under way to test the effectiveness of MTOR inhibitors in the treatment of different types of cancers." (PMID 32938364, 2020). "This implies PRR14 overexpression may be a common mechanism contributing to the PI3K/AKT/mTOR signaling pathway dysregulation in various types of cancer." (PMID 32541902, 2020). "Targeting the AKT/mTOR pathway has been considered an attractive approach in cancer treatment." (PMID 32508655, 2020). "PI3K and Akt being upstream factors of mTOR might be suitable therapeutic targets in numerous cancers." (PMID 33292283, 2020). "The present review will focus on dual PI3K/mTOR inhibitors in clinical and pre-clinical development for patients that are affected by hematological malignancies after providing an overview of the pathway in relation with cancer." (PMID 32033478, 2020).
cancer (continued). "The PI3K/Akt/mammalian target of rapamycin (mTOR) signaling cascade governs critical cellular processes, including cell growth, proliferation, metabolism, and motility, all of which are required by diverse human cancers to survive, grow, and metastasize." (PMID 33322834, 2020). "In addition, decreased K48-linked ubiquitination of mTOR by E3 ligase FBX8 and FBXW7 alleviates proteasome-dependent degradation of mTOR, exerting an oncogenic effect in cancer as well." (PMID 33004065, 2020). "As alternative mTOR pathways may sustain cancer cell survival in the presence of alpelisib and PI3Kα inhibition, we examined whether concurrent mTOR inhibition potentiates alpelisib mediated inhibitory effects." (PMID 33318517, 2020). "The PI3K/mTOR is shown in dysregulation pathway in various cancer cells." (PMID 32351887, 2020). "Furthermore, high expression levels of MMP25 were associated with many pathways in cancer, for instance, KRAS signaling pathway, apoptosis, PI3K/AKT/mTOR signaling pathway, and JAK/STAT signaling pathway." (PMID 32850314, 2020). "Therefore, targeting mTOR signaling attenuates the production of multifarious secretions, which provide an alternative option for cancer treatment." (PMID 33292459, 2020). "Observations from cancer cells strongly indicate crosstalk between Hh and mTOR signaling." (PMID 33081032, 2020). "Indeed, cancer cells hijack the PI3K/Akt/mTOR pathway to promote the induction of survival signals, inhibit apoptotic or cell death signals and acquisition of chemoresistant phenotypes." (PMID 32276377, 2020). "Therefore, the molecular mechanism behind tumor-intrinsic PD-1 needs to be elucidated in other cancer types to confirm this potential role of mTOR in PD-1 signaling in tumor cells." (PMID 33193345, 2020). "Moreover, EHop-016, a Vav/Rac inhibitor developed by us, was recently shown to overcome resistance by combined cancer therapy with Akt/mTOR inhibitors." (PMID 32322580, 2020). "In this study, we investigated the association between expression of p-Akt, p-mTOR and p-eIF4E proteins and clinicopathological characteristics in 341 cases of NSCLC and 91 cases of non-cancer lung tissues by immunohistochemistry (IHC) using high-throughput tissue microarray." (PMID 32023262, 2020). "Because mTOR is a validated therapeutic target for cancer, miRNAs inhibiting mTOR signaling may provide a novel approach to facilitate an integrated anti-cancer therapy." (PMID 33364499, 2020). "Among these downstream effectors, there are other molecules targeted by miR-193a-3p or miR-193a-5p: KRAS, a target of miR-193a-3p, and PIK3R3 and mTOR, targets of miR-193a-5p, which are all proteins stimulating proliferation, cell cycle progression, and cell survival in cancer cells." (PMID 32867069, 2020). "Recently, a new inhibitor targeting the prominent cancer signaling pathway mTOR was discovered (Rapalink-1), but its therapeutic potential on stem cell populations of GBM is unknown." (PMID 33371210, 2020). "The AKT/mTOR signaling pathway has been demonstrated to be involved in the proliferation and metabolism of cells, thus playing an important role in the occurrence and development of cancers." (PMID 32363163, 2020). "Furthermore, treatment with BEZ235 was found to suppress the cancer cell proliferation, migration, and invasion by regulating the Akt/mTOR pathway." (PMID 32466169, 2020). "Also, mTORC1 is activated in up to 80% of human cancers, while current mTOR inhibitors are of limited clinical efficacy due to resistance invoked by de-suppression of mTOR feedback networks and due to worrisome side effects." (PMID 32695336, 2020). "The PI3K/AKT/mTOR pathway has been suggested as a potential target for cancer therapy." (PMID 32818022, 2020).
cancer (continued). "The Akt/mTOR signaling pathway is a considerable regulator for the biosynthesis of protein and plays an important role in controlling cell growth in various types of cancer cells." (PMID 32401800, 2020). "Among the detected pathways, the PTEN and mTOR pathways, which are known to be effective targets in genetic tumor syndromes and cancer, are specifically deregulated in merlin-inactive NF2-associated VS after irradiation, with the PTEN pathway being down and mTOR pathway being upregulated." (PMID 31936793, 2020). "Finally, flavonoids also have anti-proliferative effects on cancer cells through suppression of the PI3k/Akt/mTOR pathway and activation of T CD4+." (PMID 32138292, 2020). "Furthermore, the PI3K/AKT/mTOR signaling pathway has been reported to be involved in regulating autophagy in cancer cells." (PMID 32024814, 2020). "The PI3K/Akt/mTOR pathway exists as one of the most attractive targets to block cancer progression." (PMID 32443845, 2020). "The PI3K/Akt/mTOR pathway is up-regulated in more than 70% of cancer types." (PMID 32793477, 2020). "Furthermore, major regulators of cancer cell growth and proliferation, such as the phosphorylated forms of Akt and mTOR, were also decreased, resulting in a significant reduction of cell proliferation in DGKζ knockdown cells compared to control cells." (PMID 32722576, 2020). "In addition, there is evidence that this methyltransferase acts on gastrointestinal tumor cells through the regulation of the PI3K/AKT/mTOR and ErbB pathways, as well as promotes the proliferation of cancer cells." (PMID 33255823, 2020). "New PI3K--AKT--mTOR inhibitors with increased potency and selectivity offer further promise, along with next-generation delivery systems that are under investigation as precision anti-cancer modalities." (PMID 33105713, 2020). "Given the integral role that the mTOR pathway plays in regulating cell growth and proliferation, it is not surprising that its over-activation is characteristic of many types of cancers due to the selective advantage it provides to cancer cells." (PMID 32341756, 2020). "Aberrant mTOR signaling pathway induces high glucose synthesis by lactic acid fermentation even when oxygen is sufficient (Warburg effect) which aids the survivial and progression of cancer cells." (PMID 32384682, 2020). "Like other types of cancers that revealed important pathological impacts of the PI3K/AKT/mTOR pathway in cancer growth and metastases, mechanistic insights of GBC pathogenesis have advanced our knowledge that this pathway predominantly contributes to the initiation and progression of GBC." (PMID 33028805, 2020). "In addition, current research is designed to optimize the use of VEGF/VEGF receptor inhibitors and mTOR inhibitors for combination or sequential treatment of patients with advanced cancer." (PMID 32070055, 2020). "Studies on PI3K/Akt/mTOR have also focused on cancer research." (PMID 32211045, 2020). "Thus, the PI3K/mTOR signalling pathway represents an important therapeutic target to induce cancer cell death." (PMID 33381351, 2020). "This suggests that these may participate in the mTOR signaling pathway, pathways in cancer, and the MAPK signaling pathway in PDAC." (PMID 32257946, 2020). "Polypyrimidine proximal to 5′ end of these genes is a target for translation regulation and may serve as a target in oxidative and metabolic stress, or cancer induced differential translation regulation by the mTOR pathway." (PMID 31924754, 2020). "Cancer therapies (radiation, biological agents, and chemical) target the immune system, pyrimidine analogues target replicative immortality, cisplatin targets apoptosis, and mTOR inhibitors alter cell signaling and affect tumor metabolism." (PMID 32498358, 2020). "Furthermore, mounting evidence demonstrates that curcumin is capable of targeting undifferentiated and highly tumorigenic cancer stem cells, and especially GCSs, through the modulation of the mTOR-dependent ATG pathway." (PMID 33092261, 2020).